PLEC (plectin)
Diseases named in the same sentence as PLEC in open-access papers (continued):
Sharing a sentence is not in itself a finding about the gene and the disease.
tumor (continued). "This study designed and successfully synthesized [99mTc]Tc-HYNIC-PTP to develop a plectin-targeting probe for tumor imaging." (PMID 35631582, 2022). "Many studies have emerged implicating that PLEC (plectin) was a pro-tumorigenic regulator of tumor proliferation, migration, and invasion." (PMID 36185199, 2022). "In in vivo tumor formation assays, depletion of plectin resulted in low-density tumors with large intercellular spaces." (PMID 36038818, 2022). "Plectin is a candidate biomarker for certain types of tumors because its expression in tumor specimens is higher than that in surrounding normal tissues." (PMID 36038818, 2022). "Although this probe holds great potential as a novel strategy for tumor imaging, further studies are needed to verify its validity in other plectin-overexpressing tumors and acquire sufficient preclinical data before clinical trials." (PMID 35631582, 2022). "Tumors with higher plectin expression levels had better T/M ratios, indicating a higher tumor uptake." (PMID 35631582, 2022). "So far, the following targets have been investigated- imaging tumour vasculature, tumour epithelial cells, plectin 1, receptor tyrosine kinase axl, bombesin receptors and MUC4 MRI approach." (PMID 35626142, 2022). "To date, plectin-targeting antibodies and peptides have been used to construct tumor-targeting imaging agents and drug delivery systems." (PMID 35631582, 2022). "Plectin is a candidate biomarker of certain tumors because of its high expression and the target of anti-tumor reagents such as ruthenium pyridinecarbothioamide." (PMID 36038818, 2022). "Quantitative analysis showed that plectin expression levels in the selected tumor cells followed the order from lowest to highest: BEAS-2B, U87, C6, A549, 4T1, and BxPC-3." (PMID 35631582, 2022). "A biodistribution experiment was performed in C6 and 4T1 tumors to validate the correlation between tumor uptake and plectin expression." (PMID 35631582, 2022). "The results revealed strong fluorescence signals in the U87, C6, A549, 4T1, and BxPC-3 cells compared with BEAS-2B cells, suggesting plectin overexpression in these tumor cells." (PMID 35631582, 2022). "More importantly, [99mTc]Tc-HYNIC-PTP showed favorable biodistribution, fast blood clearance, and clear tumor accumulation in these different tumor models, and tumor uptake showed a good correlation with their plectin expression levels." (PMID 35631582, 2022). "In this work, the authors observed how GroEL was able to protect Dox from unwanted degradation in the blood until the chaperonin reached the tumour, where GroEL interacts with plectin, which is highly expressed on the membranes of the tumour cells." (PMID 33671209, 2021). "Plectin plays a critical role in facilitating cell proliferation and tumor growth across different tumor types (Figure 3AIII)." (PMID 34571895, 2021). "Plectin is a pro-tumorigenic protein whose endogenous suppression by shRNA or siRNA inhibited proliferation, migration, and invasion in vitro and reduced tumor volume and metastases in vivo." (PMID 34571866, 2021). "Consistently, in orthotopic PDAC models with immunocompromised and immunocompetent mice, plectin-knockdown tumors have demonstrated reduced tumor growth." (PMID 34571895, 2021). "In a subcutaneous xenograft model, mice bearing OSCC plectin-knockdown tumors demonstrated decrease tumor growth." (PMID 34571895, 2021). "Knockout experiments have emphasized the profound anti-tumor effects of disrupting plectin function." (PMID 34571895, 2021). "In accordance, plectin IHC and qPCR also demonstrated a significantly higher abundance of plectin in OSCC tumor tissue compared to normal epithelium." (PMID 34571895, 2021). "In HCC, IHC staining and Western blot analysis have demonstrated that plectin is downregulated in patient tumor tissue compared to healthy liver tissue." (PMID 34571895, 2021).
tumor (continued). "In this study, we show that plectin is highly expressed on the surface of subpopulations of tumor cells within a panel of NSCLC cell lines." (PMID 31628412, 2019). "Tumor cells isolated with PCS2 or anti-plectin antibodies displayed increased expression of CSC related genes, and plectin knockdown led to dramatically impaired tumor colony formation and migration/invasion." (PMID 31628412, 2019). "To show that plectin is indeed expressed on the tumor cell surface, we used Pierce Cell Surface Protein Isolation Kit (Thermo Fisher)." (PMID 31628412, 2019). "Two cytoskeletal related proteins, vimentin and plectin, which are known tumor biomarkers, were also upregulated in IDC samples compared to normal tissue." (PMID 30154546, 2018). "Normal epithelium revealed weak or partly moderate staining restricted to the lower layers for both fascin and plectin, whereas tumor cells showed variable distribution and intensity of fascin and plectin." (PMID 29088820, 2017). "The mRNA levels of plectin were also significantly higher in the group of OSCC samples (p<0.05), but 2 tumor samples showed lower plectin levels than the normal mucosa reference pool." (PMID 29088820, 2017). "In a multivariate analysis of the N0-cases including plectin and tumor size (T1 vs T2-4), only high plectin expression was a significant independent predictor of increased DSD (p = 0.014, HR 3.674, CI 95 % 1.305-10.344)." (PMID 26306491, 2015). "The pleomorphic tumor cells were arranged in irregular nests and plectin-staining revealed weak signals." (PMID 25774093, 2015). "The expression of plectin in HCC tissues showed different expression patterns of plectin from that of the non-tumor tissues." (PMID 25774093, 2015). "In the present study the prognostic value of plectin in OSCC was evaluated by a TMA-based immunohistochemical analysis of primary tumor tissue obtained from a North Norwegian cohort of 115 patients." (PMID 26306491, 2015). "Although the cohort was small and heterogeneous, they found that the survival was significantly decreased when the tumor cells expressed high levels of plectin." (PMID 26306491, 2015). "In the present study the potential prognostic value of plectin was evaluated by a tissue microarray (TMA) based immunohistochemical analysis of primary tumor tissue obtained from a North Norwegian cohort of 115 patients diagnosed with OSCC." (PMID 26306491, 2015). "The immunofluorescence showed that the plectin and uPAR staining was localized to the same areas of the tumor." (PMID 26306491, 2015). "In contrast, the hepatocytes appeared uniform cuboid arranged in sheets or plate pattern with strong plectin signals in the non-tumor cytoplasm." (PMID 25774093, 2015). "The Plectin-1 Targeted Peptide (PTP) modified AAV2 capsid was shown to localize to tumor xenografts in mice indicating that the natural tropism of the AAV2 capsid for hepatocytes was dramatically altered." (PMID 23616947, 2013). "Plectin dysregulation also contributes to the modulation of the tumor immune microenvironment." (PMID 41011568, 2025). "Notably, PlecΔAlb mice more frequently formed larger tumors, as reflected by overall tumor size increase, possibly implying reduced migration or increased cohesion of plectin-depleted cells." (PMID 40052672, 2025). "To test whether HCC onset and progression are sensitive to pharmacological targeting of plectin, we monitored Myc;sgTp53-driven tumor development in Plecfl/fl, PlecΔAlb, and PST-treated Plecfl/fl male mice using MRI." (PMID 40052672, 2025). "We and others have proposed that plectin plays a central role in tumor growth and dissemination." (PMID 40052672, 2025). "Notably, MACF1 and plectin act as tumor promoters in CRC by affecting the cytoskeleton and intercellular interactions, thereby promoting cell migration." (PMID 41169522, 2025). "Plectin dysregulation has emerged as a critical driver of tumor progression." (PMID 41011568, 2025).
tumor (continued). "Additionally, Cheng (2015) noted heterogeneous morphology and relatively weak plectin staining in tumor regions of HCC patient tissues." (PMID 41011568, 2025). "Plectin has been shown to have both tumor-suppressive and tumor-promoting roles." (PMID 40565351, 2025). "Notably, the inhibition of exosome secretion via the knockout of Ras-related protein Rab-27A significantly impairs tumor growth, while supplementation with plectin-positive exosomes reverses this effect." (PMID 41011568, 2025). "Plectin-targeted, tumor- responsive nanopolyplex targeted PDAC cells and stroma." (PMID 41169522, 2025). "Thus, both CRISPR/Cas9-based and pharmacological plectin inactivation in HCC potently inhibits metastatic load in the lungs, identifying plectin as a potential target against tumor dissemination in vivo." (PMID 40052672, 2025). "However, later in tumor development, the presence of oncogenes such as Ras can shift plectin’s role to one of promoting tumor growth through the Erk pathway." (PMID 39334817, 2024). "Moreover, downregulation of plectin increases Rac1 activity, thereby promoting tumor cell migration." (PMID 39334817, 2024). "This suggests a potentially vital role of plectin in ameliorating tumor-induced edema." (PMID 38263015, 2024). "Besides the critical role of plectin in cellular physiological processes, an even more important role of plectin in pathological process, especially in tumor initiation and progression, has been identified in recent years." (PMID 39334817, 2024). "In addition to normal physiological functions in the cytoplasm, plectin is mislocalized on the cell membranes of tumors and is involved in a series of cellular activities, including tumor proliferation, migration, and invasion." (PMID 35631582, 2022). "Furthermore, the plectin expression levels in different tumor cells (U87, C6, A549, 4T1, and BxPC-3) were compared with those in BEAS-2B cells (negative control) using immunofluorescence staining assays." (PMID 35631582, 2022). "In addition, favorable biodistribution, fast blood clearance, and clear accumulation of [99mTc]Tc-HYNIC-PTP in several types of tumors were observed, with a good correlation between tumor uptake and plectin expression levels." (PMID 35631582, 2022). "The observation that decreased expression of the PLEC gene enhanced virus replication is consistent with earlier studies demonstrating that manipulation of cytoskeletal components enhances VSVΔ51 replication and oncolysis in various tumour models." (PMID 35393414, 2022). "However, these mice’s T/M ratios at different time points showed inconsistent trends, probably related to the tumor plectin status." (PMID 35631582, 2022). "Notably, after quantitative analysis, the fluorescence intensities followed the same order as their plectin expression levels in tumor cells, and BxPC-3 cells showed the highest FITC signal intensities." (PMID 35631582, 2022). "Plectin may also be necessary for cell anchoring to the target tissue during metastasis or separation of cells from the primary tumor mass." (PMID 36038818, 2022). "Importantly, as expected, tumors with higher expression levels of plectin possessed better tumor uptake and T/M ratios." (PMID 35631582, 2022). "Indeed, an exploration into the function of the plectin mislocalized to the cell surface has demonstrated a role in many tumor processes, including cell cycle, migration, and immune escape, pointing to the potential of anti-CSP antibody therapy." (PMID 34571895, 2021). "CSP expression was evaluated in tumor tissue samples by IHC staining for plectin." (PMID 34571866, 2021). "Moreover, plectin expression levels not only serve as a biomarker and tumor target for drug systems but correlate with a worse prognosis, suggesting a role in tumorigenesis." (PMID 34571895, 2021).
tumor (continued). "In contrast, in mouse epidermal tumor-initiating cells, depletion of plectin by shRNA was shown to increase tumor growth; however, these observations are limited by 70% of the plectin shRNA tumors, demonstrating re-expression of plectin in 30% of its cell population." (PMID 34571895, 2021). "Normally cytosolic, plectin is detected on the outside cell surface of tumor cells." (PMID 34571895, 2021). "Interestingly, plectin was also significantly overexpressed in liver hepatocellular carcinoma, suggesting nuance in the interpretation of IHC results, demonstrating decreased plectin expression in tumor tissue." (PMID 34571895, 2021). "The human tumor cells retained the expression of plectin-1, a putative PDAC biomarker." (PMID 26934555, 2016). "Double immunofluorescence staining was performed on some selected tumors to investigate whether plectin and uPAR were co-located within the same cells, co-expressed by the same cells, or located to the same tumor regions." (PMID 26306491, 2015). "Most of the tumor cells that expressed plectin also expressed uPAR." (PMID 26306491, 2015). "In plectin-positive OSSC tumors the staining was relatively homogeneous throughout the tumor." (PMID 26306491, 2015). "We choose plectin-1 positive PANC-1 cells to generate subcutaneous tumor xenografts in mice." (PMID 23616947, 2013). "However, its knockdown has been shown to promote carcinogenesis by disrupting the homeostasis of the stratified squamous epithelium (SSE), indicating that plectin downregulation may also contribute to tumor progression." (PMID 41011568, 2025). "In BCC, the significant reduction in plectin may lead to improper synthesis or assembly of HDs’ anchor filament complexes, potentially contributing to alterations in adhesive structures around the tumor periphery." (PMID 39334817, 2024). "This suggests that the expression levels of plectin may be associated with the positive or negative status of PTEN in tumor cells." (PMID 39334817, 2024). "Hence, plectin-targeting agents have great potential as imaging probes for tumor diagnosis." (PMID 35631582, 2022). "However, the relationship between plectin and Src activation in tumor cells is unclear." (PMID 36038818, 2022). "Previously we have shown that plakins (PPL, DSP, PLEC, EVPL) expressed in the ascites-derived tumour cells from patients with chemotherapy-treatment associated recurrence were significantly lower than plakins (PPL, DSP, EVPL, PLEC) in chemonaive ascites-derived tumour cells." (PMID 34001250, 2021). "In HCC, plectin is upregulated and promotes tumor cell motility through the activation of EMT and ERK1/2 signaling, whereas silencing plectin in HNSCC or HCC significantly inhibits migration and invasion." (PMID 41011568, 2025). "Using 17 distinct HCC patient datasets, we confirmed that plectin gene (PLEC) expression is consistently and significantly increased in HCC samples when compared to non-tumor (NT) liver tissues." (PMID 40052672, 2025). "In this study, we prepared a plectin-targeting imaging agent, [99mTc]Tc-HYNIC-PTP using a simple method with high RCP and stability and evaluated its feasibility as a SPECT probe for tumor imaging." (PMID 35631582, 2022). "Other proteins of specific interest down regulated in CR tumor cells were members of plakin family such as PPL, EVPL and Plectin which function as ‘molecular bridges’ linking the intracellular cytoskeleton and cell-cell junctions." (PMID 27470985, 2016). "Within HDs, plectin forms a stable adhesion complex with type XVII collagen (Bullous pemphigoid antigen 180) and the integrin α6β4, which is essential for maintaining the balance between cell adhesion and motility in tumor cells." (PMID 41011568, 2025). "More importantly, even if in the same type of tumor (e.g., HCC), while studies have found that high expression of plectin promotes tumor progression, other studies have also reported an inhibitory effect of the high expression of plectin in HCC cells." (PMID 39334817, 2024).
tumor (continued). "After SPECT imaging, the plectin expression levels in tumors were confirmed by immunohistochemistry to analyze the correlation with tumor uptake, and muscle tissues were set as the negative control." (PMID 35631582, 2022). "Increasing evidence has demonstrated that plectin affects cell migration and invasion and metastasis of neoplasm, but the molecular mechanisms involved are not fully understood." (PMID 36613521, 2022). "The authors also note that integrin β4 can act as either a tumor suppressor or oncoprotein, with plectin’s recruitment to the plasma membrane required for integrin β4’s tumor-suppressive effects in the absence of oncogenic RAS." (PMID 34571895, 2021). "Cell surface plectin expressing NSCLC subpopulations isolated by PCS2 binding have increased clonogenicity and migration/invasion characteristics compared to plectin− (plectin absent on the cell surface) NSCLC subpopulations from the same tumor line." (PMID 31628412, 2019). "Collectively, these studies highlight plectin as a central integrator of cytoskeletal remodeling, mechanotransduction, and the EMT process, coordinating intracellular tension, adhesion dynamics, and mesenchymal plasticity to drive metastatic dissemination across diverse tumor types." (PMID 41011568, 2025). "Consistent with expression analysis, quantitative immunofluorescence microscopy of 19 human HCC tissue sections revealed a significant increase of plectin fluorescence intensities in tumor (T) compared to adjacent non-tumor (NT) tissue, with plectin perimembranous enrichment in tumor hepatocytes." (PMID 40052672, 2025). "In this study, we developed a [99mTc]Tc-labeled plectin-targeted peptide (PTP) as a novel single-photon emission computed tomography (SPECT) probe for tumor imaging and investigated its pharmacokinetics, biodistribution, and targeting ability in several types of tumor-bearing mouse models." (PMID 35631582, 2022). "Recent evidence reveals that the dysregulated expression of plectin modulates the cellular and non-cellular architecture of the tumor microenvironment (TME), thereby facilitating a supportive niche for tumor invasion and dissemination." (PMID 41011568, 2025). "We found that plectin upregulation in HD-depleted cells occurred specifically in the absence of PTEN expression, a well-known tumor suppressor frequently lost in PCa." (PMID 35773413, 2022).
myopathies (7 papers, 2016 to 2025). "Our study demonstrates that EBS-MD causing PLEC mutations universally result in a desmin protein aggregate myopathy phenotype despite marked differences in individual plectin protein expression patterns." (PMID 27121971, 2016). "Obscurin and plectin are both very large proteins involved in intermediate filament stabilization, and mutations in these proteins are known to be associated with various myopathies." (PMID 36831224, 2023). "Our study demonstrates that EBS-MD causing PLEC mutations, though leading to marked differences in the individual plectin protein expression pattern, all result in a desmin protein aggregate myopathy phenotype." (PMID 27121971, 2016). "In the context of myofibrillar myopathies, mitochondrial pathology has been reported in patients with mutations in filamin-C, myotilin, ZASP, FHL1, plectin, and desmin." (PMID 27393313, 2016).
infection (5 papers, 2016 to 2025). The state of being infected such as from the introduction of a foreign agent such as serum, vaccine, antigenic substance or organism. "Plectin was almost undetectable in transduced cells two weeks after infection (asterisks)." (PMID 27007410, 2016). "Only three proteins (GSN, PLEC, and STRIP1) and one transcript (MYOM3) related to the cytoskeleton organization and dynamics were regulated in the lower trachea after infection with huH1N1." (PMID 39247193, 2024). "In this study, we identify ARID1A, PLEC and HDAC4 as predicted amiR-4 targets and show reduced gene expression and protein levels following VSVΔ51-amiR-4 infection." (PMID 35393414, 2022). "We found that the gene products encoded by ARID1A, PLEC and HDAC4 but not MCM2 were specifically decreased following infection with VSV∆51-amiR-4 as shown by RT-qPCR and immunoblotting analysis." (PMID 35393414, 2022).